RNU6-522P (RNA, U6 small nuclear 522, pseudogene)
Gene: Small nuclear RNA gene on chromosome 6 (15,314,920 to 15,315,026, forward strand). Ensembl gene ENSG00000201367.
Homologues: Orthologues: chimpanzee U6 (100% identical), macaque U6 (97% identical), pig U6 (82% identical). Paralogues in human: RNU6-1060P (90% identical), RNU6-116P (89% identical), RNU6-672P (89% identical), RNU6-12P (88% identical), RNU6-13P (88% identical), RNU6-15P (88% identical), RNU6-19P (88% identical), RNU6-32P (88% identical), RNU6-33P (88% identical), RNU6-41P (88% identical), RNU6-949P (88% identical), RNU6-1 (87% identical), and 1285 more.